CD70 (CD70 molecule)
Diseases named in the same sentence as CD70 in open-access papers (continued):
Sharing a sentence is not in itself a finding about the gene and the disease.
tumor (continued). "In addition, it has been reported that anti-CD70 CAR T-cell therapy eliminated primary CD70-positive cells and had strong anti-tumor effects in preclinical animal models." (PMID 31867275, 2019). "Immunohistochemical staining of tumor sections showed DLBCL with expression of CD19 and CD70." (PMID 31867275, 2019). "Since CD70 is absent on normal epithelial tissue, the overexpression on tumor cells can be safely exploited by CD70-targeting antibody-dependent cellular cytotoxicity (ADCC)-inducing antibodies, such as ARGX-110." (PMID 29088768, 2017). "In contrast, animals treated with isotype control-TTC (500 kBq/kg) showed no statistical significant decrease in tumor volume compared to vehicle demonstrating the specificity of the CD70-TTC." (PMID 28915592, 2017). "In animals treated with CD70-TTC, the tumors had decay corrected average activity of (9.66 ± 3.86) kBq/g 227Th corresponding to (122 ± 42) % of injected dose/gram (% ID/g) in the tumor." (PMID 28915592, 2017). "Strong immunofluorescent staining for CD70 was confined to tumor cells and did not co-localize with the T cell marker CD3." (PMID 25792975, 2015). "CD70 and CD27 expression in the tumor microenvironment was analyzed in 42 primary NSCLC samples." (PMID 25951351, 2015). "High serum sCD27 levels were found to be significantly associated with poor OS and PFS and even though sCD27 levels were not predictive of CD70 overexpression on tumor cells, dual positivity of CD70 and sCD27 marked an even worse prognosis." (PMID 25951351, 2015). "CD70 expression in tumor lesions was heterogeneous and restricted to tumor cells and not attributed to infiltrating T cells." (PMID 25792975, 2015). "Both high-passage cell lines and low-passage primary tumor cultures showed homogenous but different CD70 expression levels (or were negative) which did not seem to change after further culturing (data not shown)." (PMID 25792975, 2015). "Immunohistochemical analysis of tumor samples revealed that mice with tumor cells expressing soluble CD70 had greater infiltration of CD8+ T cells in the tumor periphery, and that depletion of CD8+ T cells reversed the benefits of soluble CD70 to overall survival." (PMID 24779345, 2014). "Additionally, the up-regulation of CD5, CD24, CD70, CD226 and PDCD1 (PD-1) that usually express on the surface of T cells, B cells, dendritic cells, NK cells, and tumor cells have also been observed." (PMID 23191987, 2012). "Taken together, enhancing CD70 expression on DCs would lead to the development of a vaccine strategy capable of facilitating the CD27/CD70 interaction, and hence the induction of an adequate anti-tumor or antiviral immune response." (PMID 22851815, 2012). "Model development with SK-OV-3 revealed that expression of CD70 was significantly down modulated in subcutaneous tumour xenografts with a lack of consistency between tumour samples (data not shown)." (PMID 20664585, 2010). "Profiling of CD70 across a broad array of tumour samples has been limited by the lack of an available antibody that reacts specifically with CD70 in FFPE tissues." (PMID 20664585, 2010). "With the limited normal tissue distribution, aberrant expression in tumours, and cell surface expression with no observed shedding of the antigen, CD70 is an attractive target for antibody–drug conjugate (ADC)-based therapy." (PMID 20664585, 2010). "In a number of cases, we also observed infiltrating leukocytes within the tumours that were CD70+ (data not shown)." (PMID 20664585, 2010). "We have previously shown that two co-stimulatory molecules (CD70 and CD80), expressed on the surface of tumor cells could induce an anti-tumor immune response when the cells were injected into a syngeneic animal." (PMID 15279677, 2004). "To determine whether the local expression of CD70 and CD80 could affect tumor establishment, we sub-cutaneously injected 105 cells, from each type of tumor, into the flanks of C57BL/6 mice." (PMID 15279677, 2004).
tumor (continued). "CD70 expression, alone or in association with a low level of CD80 expression, was not sufficient to induce anti-tumor immunity." (PMID 15279677, 2004). "This platform leverages a multimodal mechanism of action: killing tumor cells via CAR and NKRs (e.g., NKG2D and DNAM-1), modulating the immunosuppressive TME via NKT TCR-mediated recognition of CD1d+ TAMs and MDSCs, and targeting CD70+ alloreactive T cells via CAR, thereby reducing allorejection." (PMID 40885188, 2025). "By co‐targeting CD70 and CD33, they aimed to address antigen heterogeneity in AML treatment and mitigate systemic toxicity in a preclinical model, while simultaneously redirecting untransduced bystander T cells to CD33‐positive tumour cells to enhance antitumour activity." (PMID 40629902, 2025). "In addition, CD70 expressed in fibroblasts amplifies cytokine and chemokine production, including IL6 and MCP-3, which not only support cSCC growth, but also modulate the tumor microenvironment." (PMID 41510255, 2025). "In MM, however, CD70 is aberrantly and persistently expressed on malignant plasma cells, while CD27 may be downregulated during disease progression, suggesting that CD70 signaling contributes to tumor proliferation, immune evasion, and resistance to apoptosis." (PMID 41303706, 2025). "In contrast with CD70, it is shown that high CD27 expression was associated with decreased CD45 + and CD8 + cellular densities, but only in the stroma compartment, not in tumor nests." (PMID 40205178, 2025). "KCNN4 has been shown to have positive correlations with several costimulatory molecules (CD276, CD40, CD70, CD80, CD86), immune signaling receptors (IL2RA, MICB, NT5E), and multiple TNFRSF family members, suggesting its involvement in immune modulation, inflammation, and tumor‐immune interactions." (PMID 40952239, 2025). "Furthermore, we proved the functional importance of co-stimulatory molecules by showing that co-treatment of hRT/lena-treated mice with antibodies blocking CD70, CD83, and CD86 worsened primary and, more prominently, secondary (abscopal) tumor control and diminished overall survival of the mice." (PMID 38646638, 2024). "An allogeneic anti-CD70 CAR-NK construct named CAT-248, with CRISP/Cas9-mediated knockout of CD70 to avoid fratricide and secreted IL15 to facilitate persistence, has shown activity in vitro and in a xenograft RCC model where a >99% reduction in tumour burden was observed vs. controls (p < 0.01)." (PMID 38539542, 2024). "High expression of CD70, a protein belonging to the tumor necrosis family, was reported in TETs, and CD70-targeted CAR T cells were confirmed both in vitro and in vivo to be effective against tumors, indicating the possibility of CD70-targeted CAR T cell therapy for TETs." (PMID 37055838, 2023). "Higher tumor cell death might be directly due to loss of CD70 co-stimulation in co-cultured CD4+ naïve T cells and Tregs induced by CD70-NC C666 cells rather than CD4+ and CD8+ T cells in the co-culture system." (PMID 37024479, 2023). "CA9, CD70, and CD147 could represent promising markers to identify tumor-specific EVs in RCC." (PMID 36597108, 2023). "Moreover, the absence of CD70 always results in the creation of a suppressive tumor immune microenvironment via MAPK pathways, RhoE, and cytoskeletal modulation." (PMID 34367975, 2021). "We could not detect the significant difference between CD70-high and -low tumor in the levels of CD8-positive TIL or FOXP3-positive TIL; however, the number of FOXP3-positive iTIL in CD70-high TSCC was marginally larger than CD70-low TSCC." (PMID 35145909, 2021). "As CD70 is also expressed on CD8+ effector T cells and activated B cells, lack of functional CD70 might hinder T and B cell-mediated immunity to combat EBV infection and further promote tumor progression." (PMID 34568077, 2021).
tumor (continued). "In a lymphoma mouse model, it is shown that intratumoral injection of TriMix mRNA, encoding costimulatory molecules CD70, CD40 ligand, and constitutively active toll-like receptor 4 (TLR4), induces systemic tumor-specific T cell responses independent of the co-delivery of tumor antigen." (PMID 34262573, 2021). "Several of these HSEPs have been reported in other contexts to play key roles in tumour progression by cancer cell proliferation (NRSN2, WISP2, SPRX1, LCK), metastasis (GOLM1, STC1, MGAT5B), and stemness (STC1, TMEM59), as well as promoting angiogenesis (ANGPTL4) and host immunosuppression (CD70)." (PMID 33050615, 2020). "The results revealed that hypoxia stimulated cells to synthesize EVs proteins involved in enhancing tumour cell proliferation (NRSN2, WISP2, SPRX1, LCK), metastasis (GOLM1, STC1, MGAT5B), stemness (STC1, TMEM59), angiogenesis (ANGPTL4), and suppressing host immunity (CD70)." (PMID 33050615, 2020). "CD70 was highly expressed in all cases in tumor cells but not in normal tissue." (PMID 33276608, 2020). "As such, we hypothesized that due to the favorable effects on NK cells and the increase in CD70 expression upon CDDP treatment, the sequential administration of CDDP and aCD70 could increase antibody-coverage and improve NK-mediated lysis of the tumor cells." (PMID 29088768, 2017). "Moreover, anti-CD70 antibodies are considered as promising antibodies to treat human malignancies, inducing apoptosis via CD27 interaction and used to deliver drugs into the tumor." (PMID 26828592, 2016). "In addition, expression of CD4 and CD8 lymphocytes was studied in a subset of 5 patients including CD70+ and CD70− biopsies, demonstrating an increased CD4/CD8 ratio in biopsies containing CD70+ tumor cells (data not shown)." (PMID 25951351, 2015). "Thus because cell lines were homogenously positive for CD70 even if they grew from tumors in which not all cells expressed CD70, these results suggest that CD70+ cells in the tumor preferentially grow out to CD70+ primary patient-derived cultures." (PMID 25792975, 2015). "Although no expression of CD70 was found in biopsies showing ALK translocations and resistance or activating EGFR mutations, the biopsy with a T790M mutation revealed CD70 positivity in the tumor cells." (PMID 25951351, 2015). "Hence, validating the anti-tumour activity of SGN-75 on pancreatic cell lines presented a challenge because within the panel of pancreatic cell lines studied, only Panc-1 cells express CD70." (PMID 20664585, 2010). "In addition to its intrinsic effects on GSCs, POSTN can recruit microglia and upregulate CD70 expression in microglia through the αVβ3/PI3K/AKT/NFκB pathway, which in turn promotes Treg development and functionality and supports the formation of an immunosuppressive tumor microenvironment." (PMID 39227950, 2024). "In addition, the tumor lysing capacity of CARMz T cells in the mixture of CARMz T and CARP T cells was compromised upon αCD70 treatment in vitro, suggesting that CARP T cells augmented the cytotoxicity of CARMz T cells through the interaction between CD70 and CD27." (PMID 36229619, 2022). "The differences between cell culture and tumor tissue samples can be explained by the lack of contact with the microenvironment, including immune cells that might be necessary for the induction of CD70 expression." (PMID 33276608, 2020). "Moreover, it has been shown that CD70-CARTs could effectively reduce tumor burden without impairing the immune response in experimental animal models." (PMID 31867275, 2019). "Therefore it is not surprising that CD70 expression is tightly regulated in these tumor cells." (PMID 26828592, 2016). "No relation between sCD27 levels and CD70 expression on tumor cells could be detected." (PMID 25951351, 2015).
tumor (continued). "In addition, NK cell activation of DCs in anti-tumour immunity appears to depend upon tumour expression of NKG2D ligands, or expression of costimulatory molecules such as CD70, CD80 or CD86; EMT6 tumours are immunogenic respond well to PDT and may be more susceptible to immune-mediated control." (PMID 17505510, 2007). "We did notice that a high CD70+ CAF score was mostly present in samples from PDAC patients with an advanced disease stage, but the lack of adequate PDAC tumor samples from stage T1NxMx and T4NxMx is a drawback in this study." (PMID 38331849, 2024). "Our research and others in CRC indicated that CD70 expression is more abundantly found on CAFs residing in the TME, rather than on tumor cells." (PMID 38331849, 2024). "For CD70 surface expression, we found a significant increase after 5x3.0Gy in HSC-4 tumor cells; however, this effect was not visible on mRNA level." (PMID 34502022, 2021). "CD70, a TNF family member declared solely on tumor cells and not on macrophages, promotes tumor aggressiveness and immunosuppression by recruiting and activating TAMs." (PMID 34368156, 2021). "In contrast to the near absence of CD70 from normal tissues, analysis of paraffin-embedded biopsies of NSCLC revealed constitutive overexpression of CD70 in tumor cells." (PMID 25951351, 2015). "Both immunostimulatory CD8α + and CD8α- DC subsets were increased, whereas expression of activation markers CD40, CD70, CD86, and of MHC Class I molecules in either subsets of tumor infiltrating DCs were not altered by CD1d blockade." (PMID 25349699, 2014). "Although the CD70/CD27 axis has prominent immunostimulatory activity in de novo induced immune responses, its role in the established tumor micro-environment appears paradoxically opposite, with the expansion and prolonged survival of Tregs." (PMID 23840967, 2013). "Notably, in the CD70 null 786-O-FGCD70−/− metastasis model, conventional CAR70-T cells failed to control tumor growth due to the absence of their target antigen." (PMID 40885188, 2025). "CD70 expression in activated immune cells, nonneoplastic tissues, or certain non‐RCC tumours may contribute to false‐positive signals, especially under inflammatory or immune‐reactive conditions." (PMID 40629902, 2025). "Neither CD70 expression (rs = -0.0421, p = 0,713), nor CD27 + cellular density (rs = 0.0165, p = 0.881) show significant correlation with tumor stage, suggesting an expression pattern inherent to the original tumor phenotype." (PMID 40205178, 2025). "The CD27/CD70 axis is an immune checkpoint pathway that has not been fully studied and there is evidence that the CD27 plays an important role as a stimulatory immune checkpoint in tumor progression and cellular immunity." (PMID 38169519, 2024). "In oncology, CD70 is aberrantly expressed on malignant cells without (solid tumors) or with CD27 co-expression (hematological malignancies), facilitating immune evasion through the tumor microenvironment (TME) and tumor progression." (PMID 34991665, 2022). "Interestingly this CD70 expression does not affect PLX-4032-induced inhibition of MAPK pathway activation and tumor cell cytotoxicity." (PMID 26828592, 2016). "Moreover, simultaneous silencing of CD70 and treatment with PLX-4032 did not alter PLX-4032-induced inhibition of tumor cells proliferation." (PMID 26828592, 2016). "Similarly the ectopic expression of CXCR1, which is not normally expressed on T cells, or CXCR2, on anti-CD70 CAR T cells, enhanced the trafficking to tumours and elicited tumour regression and improved survival in models of glioblastoma, pancreatic cancer, and ovarian cancer." (PMID 35205725, 2022).
cancer (143 papers, 2006 to 2026). A tumor composed of atypical neoplastic, often pleomorphic cells that invade other tissues. "In solid tumors, CD70 signaling associates with cancer stemness and epithelial-mesenchymal transition (EMT) by upregulating EMT-related genes (SOX2, CD44, vimentin, Snail, Slug, β-catenin) while activating MAPK and overexpressing RhoE." (PMID 40896423, 2025). "CD70 expression has been associated with immune escape mechanisms in various cancers, including LUAD, through its interaction with the CD27 receptor on T cells." (PMID 40458414, 2025). "ENHO also demonstrated negative correlations with immune checkpoint molecules CD276 (B7-H3) and CD70, both of which are associated with immune suppression and adverse outcomes in cancer." (PMID 40647442, 2025). "Many different types of cancer, both hematologic and solid, have been linked to abnormal expression of CD70 and its receptor CD27." (PMID 37849799, 2023). "As ectopic or aberrant expression of CD70 is potentially associated with clinical courses in several types of cancer, we next studied the value of CD70 protein expression for predicting survival." (PMID 36471481, 2022). "Upregulated CD70 expression has been observed in various types of malignancies, being linked with poor clinical outcomes and prognosis in certain cancers such as breast cancer and B cell lymphoma." (PMID 35585975, 2022). "Induction of CD70 expression has also been linked to cancer types caused by viral infections, such as Epstein-Barr virus and Human T-lymphotropic virus type 1." (PMID 34991665, 2022). "In pan-cancer significant association of CD70 and LAG3 expression with poor survival was observed (p < 0.05)." (PMID 35690832, 2022). "The lymphoid malignancy observed in the CD70-deficient proband and various other cancers in the family members suggest that CD70 has a potential role in preventing tumorigenesis." (PMID 33996677, 2021). "CD70 expression is very limited in the steady state, although increased levels of CD70 have been reported to be associated with inflammatory conditions such as chronic viral infection, cancer, or autoimmune disease." (PMID 32665635, 2020). "Moreover, CD70 is also expressed on cancer-associated fibroblasts (CAFs), another roadblock for treatment efficacy in CRC and PDAC." (PMID 38331849, 2024). "In addition, gene expression studies showed that CD70 was overexpressed in basal-like compared to Luminal A cancers and that overexpression after NACT was associated with a better outcome." (PMID 31060337, 2019). "These indicated the dependence of cancer cell growth on CD70-associated pathways." (PMID 29721188, 2018). "Here, we report that HIF-2α up-regulates the expression of CD70, a cancer-related surface antigen that improves anchorage-independent growth in cancer cells and is associated with poor clinical prognosis, which can be induced via epigenetic modifications mediated by DNMT1." (PMID 29721188, 2018). "Notably, high expression of CD70 in cancer patients has been associated with poor survival." (PMID 41233805, 2025). "Given its aberrant expression in malignancies, CD70 has become a promising target for cancer immunotherapies, such as blocking antibodies and CAR-T cell therapies." (PMID 41233805, 2025). "These CAR T cells have demonstrated potential in targeting CD70-positive malignant cells, providing a promising approach for treating cancers with high CD70 expression." (PMID 40597436, 2025). "CD70 overexpression was limited to specific HNSCC cancer subtypes such as laryngeal, oral cavity, and tongue cancers." (PMID 40675157, 2025). "Elevated CD70 levels are linked to a reduction in CD8 + T cells, which are vital for the immune system’s ability to fight cancer." (PMID 40312353, 2025). "The next-generation drug versions, CTX112 for CD19+ cancers (NCT05643742) and CTX131 (NCT06492304) for CD70+ cancers, improve on their counterparts through additional gene knockouts." (PMID 41476860, 2025).